TRIP6 (thyroid hormone receptor interactor 6)
Diseases named in the same sentence as TRIP6 in open-access papers (continued):
Sharing a sentence is not in itself a finding about the gene and the disease.
tumor (15 papers, 2011 to 2025). "Our prognostic model, the HRM, provides a clinically relevant tool for risk stratification, while its key mediator, TRIP6, represents a novel therapeutic target linking tumor metabolism to immune evasion." (PMID 41438741, 2025). "More importantly, this study expands the purview of TRIP6 from traditional signal transduction to its potential association with the regulation of the tumor immune microenvironment." (PMID 41438741, 2025). "We next investigated the association between TRIP6 expression and clinical indicators of tumor progression." (PMID 41438741, 2025). "TRIP6 functioned as an oncogenic role in various solid tumors via regulation of multiple tumor-associated signaling pathways, such as Wnt/β-catenin." (PMID 39882240, 2024). "TRIP6 expression was abnormally elevated in GBM tumor tissues and is associated with poor prognosis." (PMID 39882240, 2024). "Finally, to understand the broader genomic context of TRIP6, we explored its relationship with key markers of genomic instability—Tumor Mutational Burden (TMB) and Microsatellite Instability (MSI)." (PMID 41438741, 2025). "Collectively, these results suggest that the poor prognosis associated with TRIP6 may stem from its role in promoting an immune-cold tumor microenvironment, thereby potentially limiting the efficacy of immune-based therapies." (PMID 41438741, 2025). "Specifically, TRIP6 expression was significantly higher in tumors of a more advanced T stage (tumor size and invasion) and in patients with distant metastasis (M1) compared to those without (M0)." (PMID 41438741, 2025). "Recent studies have shown that TRIP6 was significantly upregulated in paclitaxel-resistant tumor cells, but the specific mechanism remained unclear." (PMID 39882240, 2024). "The expression levels of TRIP6 in CRC samples of different tumor stages were higher than those in normal samples." (PMID 38369589, 2024). "In this study, the inhibition of TRIP6 in LoVo cells led to a substantial inhibition of cell proliferation and growth, induction of cell cycle arrest, and facilitation of tumor cell apoptosis." (PMID 38430268, 2024). "TRIP6 is frequently overexpressed in COAD tissues and cell lines compared to normal tissues that is associated with poor prognosis, advanced tumor stage, lymph node metastasis and distant metastasis in COAD patients." (PMID 37524774, 2023). "TRIP6 expression in tumor tissues from EOC patients was lower than that in control ovarian tissue and did not correlate with the survival of patients or their therapeutic outcome." (PMID 35008510, 2021). "Subsequently, we compared the mRNA level of ABCC3, CPS1, and TRIP6 genes in EOC tumor samples with control ovarian tissues." (PMID 35008510, 2021). "While our in vitro experiments focused on tumor-cell-intrinsic functions, our computational analysis of patient data revealed a strong correlation between high TRIP6 expression and an immunosuppressive phenotype, including the downregulation of immune-activating signaling pathways." (PMID 41438741, 2025). "However, the precise role of TRIP6 in tumor metabolic reprogramming, particularly in amino acid metabolism, has long remained unclear." (PMID 41438741, 2025). "Previous studies have demonstrated that activation of TRIP6 may be induced by the transcriptional activating factor v-rel and acts as a promising target for inhibiting v-rel-induced tumor formation and transcriptional activity." (PMID 38430268, 2024). "In an endeavor to unearth the potential relationship between TRIP6 expression and immune function, we conducted a meticulous investigation on 24 immune cell populations that are present within the tumor microenvironment by leveraging the ssGSEA computational method." (PMID 38369589, 2024). "The results showed that silencing TRIP6 expression could significantly inhibit the proliferation and migration of tumor cells." (PMID 39882240, 2024).
tumor (continued). "Concurrently, results from the GSEA and gene expression correlation analysis further confirmed that TRIP6 may influence the glycolytic capacity of tumor cells by affecting the expression of a key glycolysis gene, GPI." (PMID 38369589, 2024). "TRIP6 interacts with LPA and thyroid hormones, proteins known to play a role in energy metabolism and basal metabolic rate, and implicated in the immune response to bacterial pathogens and tumor invasiveness." (PMID 21533023, 2011). "Furthermore, TRIP6 demonstrated strong diagnostic potential, with a ROC curve analysis yielding an AUC of 0.793, indicating its robust ability to distinguish tumor from non-tumor tissue." (PMID 41438741, 2025). "To gain deeper insight into whether the TRIP6 high and low expression groups display significant disparities in terms of the tumor immune microenvironment in CRC, we conducted a comprehensive evaluation of the differentiated expression of 24 variants of immune cells." (PMID 38369589, 2024). "Significantly, the pronounced correlation exhibited between TRIP6, and glycolysis-related genes, and angiogenesis-related genes, and immune cell infiltration and immune checkpoint genes suggests that it may serve as a potential target for tumor immunotherapy." (PMID 38369589, 2024). "Additionally, observations of enhanced TRIP6 expression in various neoplasms might indicate disrupted gene regulatory mechanisms during cancerogenesis." (PMID 36833223, 2023). "TRIP6 can be used as a novel biomarker for predicting GBM prognosis, tumor metastasis, and chemotherapy response, assisting in monitoring tumor progression and adjusting treatment strategies." (PMID 39882240, 2024). "Also, TRIP6 may promote angiogenesis in tumor cells by promoting the expression of JAG2." (PMID 38369589, 2024). "We evaluated the expression levels of TRIP6 in CRC tissues and non-tumor tissues using data from the TCGA database to establish a correlation between TRIP6 and CRC." (PMID 38369589, 2024). "Subsequently, we analyzed the data from 4 GEO databases to further validate the expression levels of TRIP6 in CRC tissues and non-tumor tissues." (PMID 38369589, 2024). "Subsequently, we compared the expression of mRNA levels of CPS1 and TRIP6 with their protein levels in representative sets of control ovarian tissues and EOC tumor samples divided into EOC low and high mRNA expression groups." (PMID 35008510, 2021). "Furthermore, the correlation between TRIP6 and immunostimulator genes, immunoinhibitor genes, and MHC genes further confirms its close relationship with tumor immunity." (PMID 38369589, 2024). "We compared the gene expression levels between normal and tumor tissues of COAD patients from TCGA and found that OXSM was significantly downregulated (p = 5.20 × 10–9), while TRIP6 (p = 5.00 × 10–12), MYH3 (p = 6.70 × 10–3), and MYH4 (p = 6.41 × 10–7) were upregulated in COAD tissues." (PMID 37524774, 2023). "Moreover, we searched the HPA database for immunohistochemical staining data of TRIP6 and MYH3 in tumor tissues and observed higher protein expression of these genes in analyzed tumor tissues." (PMID 37524774, 2023). "However, no studies have been reported on TRIP6 and tumor cell glycolysis, angiogenesis, and immune infiltration." (PMID 38369589, 2024). "However, there are currently no studies on the relationship between TRIP6 and CRC tumor cell glycolysis, angiogenesis, and immune cell infiltration." (PMID 38369589, 2024).
colorectal (1 paper, 2025). "Initial reports identified its role in colorectal carcinogenesis through TRIP6 stabilization-mediated potentiation of Wnt/β-catenin signaling." (PMID 40713894, 2025).
infection (1 paper, 2010). The state of being infected such as from the introduction of a foreign agent such as serum, vaccine, antigenic substance or organism. "However, S100A1, MUC1, and TRIP6 showed a continued up-regulated status at 4 days post-infection." (PMID 21172007, 2010).
neurodegenerative disease (1 paper, 2012). A disorder of the central nervous system characterized by gradual and progressive loss of neural tissue and neurologic function. "In addition, some CAMs have been shown to shuttle between FA and nucleus to regulate gene expression, including CDK5, ERK, GSK3B and COPS5 (JAB1) and members of the LIM family of proteins (PXN and Trip6), many of which have been implicated in the molecular pathology of neurodegenerative diseases." (PMID 22815752, 2012).
TRIP6 also shares sentences with these, for which no sentence is quoted: central precocious puberty (1 paper); ciliopathy (1); diabetes mellitus (1); hypothalamic hamartomas (1); lipoma (1); obstructive hydrocephalus (1); pancreatic tumors (1); prostate carcinoma (1); renal fibrosis (1); stomach cancer (1).